RSRP1 (arginine and serine rich protein 1)
Description:
Probably acts as a spliceosomal factor that contributes to spliceosome assembly and regulates the isoform switching of proteins such as PARP6.
Synonyms: C1orf63; NPD014; DJ465N24.2.1
Tractability: PROTAC: ubiquitination databases record sites on it.
Gene: Protein-coding gene on chromosome 1 (25,242,248 to 25,338,244, reverse strand). Ensembl gene ENSG00000117616.
Subcellular location: Nucleus
Subcellular location (Human Protein Atlas): Nucleoplasm
Gene Ontology:
Molecular function: protein binding
Biological process: spliceosomal complex assembly
Cellular component: nucleus
Genetic constraint (gnomAD): Loss-of-function variants: 31 observed, 29.39 expected, observed/expected ratio (o/e) 1.05, 90% interval 0.79 to 1.42. The upper end of that interval is the gene's LOEUF score, 1.42, which puts it in group 5 of 6, group 1 being the genes least tolerant of losing a copy. Missense variants: 361 observed, 373.73 expected, observed/expected ratio (o/e) 0.97, 90% interval 0.88 to 1.05. Synonymous variants: 155 observed, 157.71 expected, observed/expected ratio (o/e) 0.98, 90% interval 0.86 to 1.12.
Homologues: Orthologues: macaque RSRP1 (92% identical), mouse Rsrp1 (77% identical), guinea pig RSRP1 (76% identical), dog RSRP1 (75% identical), chimpanzee RSRP1 (73% identical), pig RSRP1 (73% identical). Paralogues in human: SRSF4 (26% identical), SRSF6 (24% identical), RSRC2 (20% identical), SRSF5 (18% identical), SRSF7 (17% identical), SRSF1 (17% identical), SRSF3 (14% identical), SRSF9 (13% identical).
Diseases named in the same sentence as RSRP1 in open-access papers:
RSRP1 is named in the same sentence as 15 diseases in open-access papers, as found by Europe PMC text mining. Sharing a sentence is not in itself a finding about the gene and the disease. The quoted sentences say what the papers report.
breast carcinoma (2 papers, 2015 to 2024). "The Arginine and Serine Rich Protein 1 (RSRP1) is involved in spliceosome assembly and has a good prognosis in breast cancer, but its biological mechanism is still unknown." (PMID 38673800, 2024).
glioblastoma (1 paper, 2025). The most malignant astrocytic tumor (WHO grade IV). "In glioblastoma, arginine/serine-rich protein 1 (RSRP1) catalyzes PARP6 exon 18 skipping, generating the truncated oncogenic form of PARP6 (PARP6-s), which lacks the catalytic triad of residues essential for MARylating activity." (PMID 40741921, 2025).
melanoma (1 paper, 2022). A malignant, usually aggressive tumor composed of atypical, neoplastic melanocytes. "The prognostic signature based on the OS-ireRNAs included AC009495.2, LINC02446, LINC00189, RSRP1, CUTALP, CMAHP and MOSMO, and accurately predicted the prognosis of melanoma patients, especially for those who survived for more than 3 years." (PMID 36338651, 2022).
RSRP1 also shares sentences with these, for which no sentence is quoted: tumor (2 papers); breast tumor (1); cancer (1); cardiac disease (1); cystadenoma (1); heart failure (1); hepatocellular carcinoma (1); infection (1); lung carcinoma (1); lymph node metastasis (1); prostate carcinoma (1); triple-negative breast carcinoma (1).